SOD1 (superoxide dismutase 1)
Diseases named in the same sentence as SOD1 in open-access papers (continued):
Sharing a sentence is not in itself a finding about the gene and the disease.
Hyperglycemia (171 papers, 2007 to 2025). An increased concentration of glucose in the blood. "Overexpression of SOD1 in the SOD1-Tg mice suppressed lipid peroxidation in the maternal hyperglycemia that leads to diminished susceptibility of diabetic embryopathy." (PMID 34326888, 2021). "ROS scavenging via the upregulation of SOD1 can alleviate hyperglycemia-induced endothelial dysfunction and improve endothelial-dependent relaxation." (PMID 40232847, 2025). "Superoxide dismutase (Sod1, Sod2) and catalase (Cat) are potent antioxidant enzymes and regulate the levels of reactive oxygen species (ROS) generated through hyperglycemia." (PMID 37110174, 2023). "Abnormal fat depositions under pathological conditions, such as primary myodystrophies, obesity, hyperglycemia, high plasma free fatty acids, and hypoxia are characterized by dysfunctional SOD1." (PMID 36078046, 2022). "SOD1 + HFD had significantly increased glucose levels compared to SOD1 + ND and Wt + ND, indicating hyperglycemia, possibly due to decreased glucose metabolism." (PMID 33931719, 2021). "Compared to EVs from control cells, EVs secreted from cardiomyocytesHSP20 exhibited elevated levels of p-protein kinase B (pAkt), survivin and superoxiddismutase 1 (SOD1) and protected against in vitro hyperglycemia-triggered cell death." (PMID 30356109, 2018). "The authors of the present study investigated antioxidant status at the very early stages of hyperglycemia and found lower SOD-1 activity and plasma TAS in prediabetic elderly persons in comparison with normoglycemic ones." (PMID 24891926, 2014). "Conversely, hyperglycemia suppresses protective, anti-inflammatory mechanisms by reducing the expression of JunD, as well as the critical scavengers of reactive oxygen species (ROS) like superoxide dismutase 1 (SOD1) and aldehyde dehydrogenase 2 (ALDH2)." (PMID 40149704, 2025). "Hyperglycemia also decreases the expression of protective and anti-inflammatory factors including, Jun proto-oncogene subunit (JunD), reactive species scavengers such as superoxide dismutase 1 (SOD1), and aldehyde dehydrogenase 2 (ALDH2)." (PMID 38474219, 2024). "The results showed that the SOD1 decreased under hyperglycemia in db/db mouse." (PMID 35874807, 2022). "A slight increase in the gene expressions of SOD1 and the other antioxidant enzymes in the DM1 group may be a compensatory mechanism to cope with the damage caused by hyperglycaemia in hepatocytes." (PMID 36818894, 2022). "Based on our data, attenuation of podocyte injury may be associated with reducing hyperglycemia, upregulation of SOD-1/SOD-3 mRNA expression, and downregulation of the TRPC6 mRNA expression in the CeA treatment in early hyperglycemia condition." (PMID 34326888, 2021). "However, there was little difference in SOD1 expression between hyperglycemia group and euglycemia group." (PMID 26439801, 2015). "In an experimental study examining cardiomyocytes exposed to hyperglycemia, DATS administration reduced OS primarily by increasing the expression of antioxidants (HO-1, SOD-1, and SOD-2) via upregulation of Nrf2 expression and its translocation to the nucleus." (PMID 39337318, 2024). "In the current study we shown that under hyperglycemia condition antioxidants like NQO1, SOD1 were upregulated and Gpx1 was down regulated and upon vitamin-D treatment this conditioned were normalized." (PMID 36358486, 2022). "Erythrocyte SOD-1 activity and plasma TAS are lower in elderly prediabetics in comparison with normoglycemic cases revealing deactivation of antioxidative capacity by hyperglycemia in elderly patients." (PMID 24891926, 2014). "Additionally, in an in vivo model of streptozotocin‐induced hyperglycemia and diabetes type I in rats, CV showed beneficial effects on diabetic cardiomyopathy and increased protein expression of SOD2, SOD1, and catalase in heart and skeletal muscle." (PMID 39924769, 2025).
Hyperglycemia (continued). "Overexpression of SOD1 in transgenic embryos was able to revert the molecular dysregulations of TGFβ signaling induced by maternal hyperglycemia, but the effect of SOD1 rescue on the cardiac phenotype has not been demonstrated." (PMID 38003449, 2023). "Interestingly in contrast to HUVEC, the gene expression of ROS clearance enzymes, SOD1, GPX1, TXNRD1, TXNRD2, and PRDX1 were upregulated in HMVEC under hyperglycemia." (PMID 24093550, 2013). "In addition, hyperglycaemia and dyslipidaemia perturbs renal antioxidant capacity by lowering glutathione (GSH), glutathione peroxidase-1 (GPx1), superoxide dismutase-1 (SOD1), and catalase (CAT) that subsequently induce lipid peroxidation, protein damage, and chronic inflammation." (PMID 38139208, 2023). "In the current study, we found that HG increases SOD2, but not SOD1 expression, which might indicate that hyperglycemia preferentially affect H2O2 production in mitochondria." (PMID 26439801, 2015). "In HMVEC, gene expression of SOD1 and SOD2 (non-significant) simultaneously increased with O2 ̅ levels, and CYBA (non-significant), NOX1, and NOX4 expression during hyperglycemia." (PMID 24093550, 2013). "However, during the hyperglycemia, the SOD is unable to eliminate the excess ROS, which results in suppression of the antioxidant enzymes such as SOD1, SOD3, and catalase but not SOD2." (PMID 34326888, 2021).
Obesity (170 papers, 2011 to 2026). Accumulation of substantial excess body fat. "To analyze the oxidative imbalance linked to obesity detected at the plasma level, we evaluated two important cytoplasmatic antioxidant enzymes, SOD1 and GSTP1, in adipose tissue." (PMID 33255520, 2020). "The results of previous studies showed that many disorders observed during PCOS such as impaired glucose regulation, type 2 diabetes, obesity, and inflammation could be associated with the rs2070424 polymorphism of SOD1." (PMID 35566673, 2022). "The offspring of mothers with liraglutide or dietary intervention in the perinatal period had reduced expression of SOD1 compared to the offspring of the mothers with obesity (H vs. HL, p < 0.05, H vs. HC, H vs. HPC, p < 0.0001)." (PMID 38201940, 2023). "The offspring of mothers with obesity had increased gene expression of the antioxidant marker SOD1 in the liver when compared to the offspring of lean mothers (C vs. H, p < 0.0001)." (PMID 38201940, 2023). "Superoxide dismutase (SOD1) is a target gene of ssc-miR-503 and contributes to cellular defense against superoxide radicals (antioxidants) and prevents obesity-induced changes in oxidative stress." (PMID 36078046, 2022). "Our research group previously identified an association with obesity for the SNPs 599C>T GPX1 (rs1050450) and − 251A>G SOD1 (rs2070424)." (PMID 29339975, 2018). "When adolescent female mice were subjected to a prolonged duration (26 weeks) of HFD, both SOD1 and SOD2 activities were significantly lower in all three brain subregions compared to their respective controls, underlining the marked effect of obesity duration." (PMID 39230054, 2024). "Obesity was also associated with a downregulation in the gene expression of NOX-4 (p < 0.05) and with a significant increase in the mRNA levels of GSR (p < 0.01), SOD-1 (p < 0.001) and PGC-1α (p < 0.05) in gastrocnemius muscle." (PMID 36139877, 2022). "Obesity was associated with an upregulation in the gene expression of IL-1β (p < 0.05), IL-6 (p < 0.01) and NOX-4 (p < 0.05), and with a downregulation in the mRNA levels of the antioxidant enzymes GPX-3 and SOD-1 (p < 0.01 for both) in aortic tissue." (PMID 36009292, 2022). "LF-CQPC07 upregulated the mRNA expression of SOD1, GSH-Px, SOD2, CAT, and GSH1 to increase the body’s antioxidant capacity and inhibit oxidative stress, thereby relieving liver damage and inflammation caused by obesity." (PMID 33531053, 2021). "In addition, the HFD/fucoidan-fed obese gerbils showed significant increase in the obesity-mediated decreases of levels of SOD1 and SOD2 in the pre- and post-ischemic phases." (PMID 30696078, 2019). "In keeping with our hypothesis of inflammation-induced damage to PVAT function in obesity, there are lower levels of SOD1, peroxiredoxin-1 and adiponectin in obese human PVAT." (PMID 26910225, 2015). "Similarly, in the context of obesity, NZs, like CeO2, nanoformulated SOD1, and aptamer-conjugated gold nanoclusters have effectively improved adipose tissue oxidative status, reduced pro-inflammatory macrophage infiltration, and ameliorated hepatic and systemic metabolic dysregulation." (PMID 41346708, 2026). "Several SNPs of the NRF2 gene have repercussions on certain antioxidant enzymes, for example, rs2234694 is related to SOD1, rs2536512 to SOD3, rs1056806 to GSTM1, rs4880 to SOD2 and rs1800668 to GPx1; all were found in obese patients and were associated with increased risk of obesity." (PMID 40428311, 2025). "Some studies have reported downregulation of Sod1 and Cat genes in C57BL/6J male mice fed high-calorie diets, which increases oxidative stress in obesity." (PMID 40573106, 2025). "DC attenuated the reduction in the gene expression of GSR and SOD-1 (p < 0.05 for both), whereas DCE, DCT, and DCTE completely prevented the obesity-induced reduction in the mRNA levels of NOX-4, GSR, GPX-3 and SOD-1 (p < 0.05)." (PMID 36139877, 2022).
Obesity (continued). "Obesity induced a significant decrease in the mRNA levels of NOX-4 (p < 0.05), GSR (p < 0.01), GPX-3 (p < 0.05), and SOD-1 (p < 0.05)." (PMID 36139877, 2022). "Finally, DCTE reduced the obesity-induced alterations in the gene expression of GSR (p < 0.01), SOD-1 (p < 0.05) and PGC-1α and up-regulated the mRNA levels of GPX-3 (p < 0.05)." (PMID 36139877, 2022). "Moreover, supplementation with CTE prevented the obesity-induced decrease in the gene expression of the antioxidant enzymes GPX-3, GSR and SOD-1, and increased the mRNA levels of endothelial nitric oxide synthase (eNOS) in arterial tissue." (PMID 36009292, 2022). "In contrast, and as expected, obesity produced a significant decrease in the front line of defense against reactive oxygen species—SOD1 expression—that is not modified by CIH." (PMID 34439481, 2021). "Neither Nrf2 nor Keap1 was affected by maternal obesity or grape juice intake, and antioxidant genes Ogg1, Ogg2, Sod1 or Sod2 were not affected either." (PMID 32731460, 2020). "The expression of antioxidant enzymes, including catalase, superoxide dismutase I (SOD1), and superoxide dismutase II (SOD2), in the aorta was not significantly affected by obesity and pioglitazone treatment." (PMID 33781257, 2021). "However, abundance of antioxidant enzymes such as SOD1 and SOD2, and electron transport chain complexes in skeletal muscle were not affected by obesity or dietary supplements." (PMID 38886475, 2024).
Alzheimer disease (157 papers, 2009 to 2026). A progressive, neurodegenerative disease characterized by loss of function and death of nerve cells in several areas of the brain leading to loss of cognitive function such as memory and language. "Sod1 has also been implicated in Alzheimer’s disease whereby Sod1 knockout accelerated amyloid-β oligomerisation and memory loss in an AD mouse model and conversely overexpression of Sod1 rescues the cerebral endothelial dysfunction in another AD model." (PMID 23349894, 2013). "Conversely, Sod1 loss significantly increases Aβ oligomerization, plaque formation and oxidative damage in a mouse model of Alzheimer’s disease, and conditional knockout of Sod2 in the brain is associated with increased levels of oxidative damage and lethality." (PMID 38755517, 2024). "In an aged Alzheimer’s disease mouse model, water extract of Centella asiatica improved cognitive functions via increasing the Nrf2 gene expression in the hippocampus and by reducing Aβ plaque-associated SOD1 in the hippocampus and cortex." (PMID 36118773, 2022). "Raised levels of PERK-P and eIF2α-P are observed in prion-diseased mice; in Tg4510 mice, which overexpress the frontotemporal dementia-associated human tau mutation P301L; in 5xFAD mice that express five Alzheimer’s disease-linked mutations; and in mutant SOD1-expressing mice." (PMID 27190028, 2016). "Examples of disease-associated misfolded proteins are tau and amyloid beta in Alzheimer’s disease (AD), alpha-synuclein in Parkinson’s disease (PD), TDP43 and SOD1 in amyotrophic lateral sclerosis and amylin in type 2 diabetes." (PMID 36778589, 2022). "SOD1 and SOD2 are SOD isoenzymes present inside cells, which have been reported to be associated with Alzheimer's disease." (PMID 34650664, 2021). "A decrease in the amount of SOD1 would lead to a decreased capacity to cope with oxidative stress, and SOD1 has been found oxidatively damaged in Alzheimer’s disease and Parkinson’s disease patients." (PMID 34073856, 2021). "Although most of the genes were involved in several of these pathways, some of them were restricted to Huntington’s disease (AP2B1, CREB3L4, POLR2H and SOD1), to Alzheimer ́s disease (NAE1, FAS) or to Parkinson’s disease (PARK7)." (PMID 24742402, 2014). "The elevated expression of SOD1 has been associated with a number of neurodegenerative disorders, such as SALS and Alzheimer disease, suggesting that SOD1 upregulation is a pathological phenomenon." (PMID 22432009, 2012). "Copper chaperones for superoxide dismutase activates the ROS-scavenging function of SOD1 by delivering of Cu2+ and has been proposed for treatment of Alzheimer’s disease." (PMID 23251571, 2012). "Some abnormal protein aggregation associated with neurodegenerative diseases, such as amyloid beta peptide (Aβ) in Alzheimer’s disease, α-synuclein in Parkinson’s disease, and SOD1 and TDP-43 in ALS, are known to induce the activity of the NLRP3 inflammasome in a mouse model." (PMID 37891975, 2023). "In addition, in an Alzheimer’s Disease model, triheptanoin in the context of a ketogenic diet increased the expression of the mRNA levels of Sirt1, Pparg, Sod1 and Sod2." (PMID 27564703, 2016). "Indeed, in SOD1-related ALS, Huntington's disease, and Alzheimer's disease, specific neuronal subtypes are affected despite ubiquitous expression of SOD1, huntingtin and APP, respectively." (PMID 19266020, 2009). "Our study reveals common molecular pathways in Alzheimer's disease (AD) and atherosclerosis (AS), notably in genes like BEX2, NKRF, SOD1, UBL5, ZBTB17, and ZNHIT3." (PMID 38738952, 2024). "SOD1 has not been reported in AAA, but when treated with hydroxyl ethanol, it inhibits Ang II-induced Alzheimer’s disease, decreases the expressing of NF-κB, P65, TNF-α, and IL-1β, and increases the conveying of SOD1, MMP9, and GCLC in mice." (PMID 37737183, 2023).
Alzheimer disease (continued). "The expression levels of the genes for APP (Alzheimer’s disease marker), DYRK1A, DSCR1 (Down syndrome critical region 1), ETS2, and SOD1, all of which are located on chromosome 21, are dysregulated in trisomic cells." (PMID 34433490, 2021). "SIRT1 deacetylase protects against neurodegeneration in models of Alzheimer’s disease as well as ALS, although enhancing SIRT1 activity by resveratrol did not affect functional improvement or increased longevity in an SOD1 mutant mouse model of ALS." (PMID 24312501, 2013). "The lack of motor neuron disease in SOD1 knock-out mice and the normal enzymatic activity conferred by some of the SOD1 mutants suggest a cytotoxic gain of function similar to the disease causing proteins in other neurodegenerative disorders like Alzheimer’s disease and Parkinson’s disease." (PMID 24143259, 2013). "We therefore evaluated NF-L levels in the plasma of the ALS models SOD1-G93A low expressor and TAR6/6 mice, the Alzheimer’s disease (AD) model 5xFAD, the Parkinson’s disease model Line 61 and the Gaucher disease (GD) model 4L/PS-NA and the CSF of selected models." (PMID 32595447, 2020). "We observed that human spinal cord homogenates prepared from SOD1 familial ALS (FALS) can induce significantly more intracellular reporter protein aggregation than spinal cord homogenates from sporadic ALS, Alzheimer’s disease, multiple system atrophy or healthy control individuals." (PMID 28877271, 2017). "Although Hsp70 overexpression has been shown to be beneficial in rodent Alzheimer's disease models, when Hsp70 was ubiquitously over-expressed in SOD1 mice, there was no protective effect." (PMID 22900172, 2012). "Interestingly, SOD1 showed interaction with OPTN involved in neuroinflammation, autophagy, and vesicular trafficking in ALS, FTD, Alzheimer’s disease, and Huntington’s disease." (PMID 34918006, 2022).